IL11 (interleukin 11)
Diseases named in the same sentence as IL11 in open-access papers (continued):
Sharing a sentence is not in itself a finding about the gene and the disease.
tumor (continued). "Intraperitoneal injection of recombinant IL11 (reIL11) in tumor-bearing Il11−/− mice boosted tumor growth, while STAT3 knockdown diminished such pro-tumor effect in vivo." (PMID 37365574, 2023). "MC38 cells were subcutaneously inoculated into Il11−/− mice, which presented a slower growing curve and smaller tumor weight compared with those in WT mice." (PMID 37365574, 2023). "YTHDF2 inhibits tumor cells and the tumor vascular system by regulating interleukin-11 (IL-11) and SERPINE2 mRNAs." (PMID 38072944, 2023). "Many conserved interactions involved tumour ligands associated with ER stress, such as APOE, IL11 and CCL2." (PMID 37612508, 2023). "MiR-205/YAP1/IL11/IL15 signal axis is a VEGF-independent signal transduction pathway in breast matrix CAFs but still plays a specific role in tumor angiogenesis." (PMID 37978384, 2023). "IL-11 also affects tumor cells present in the bone microenvironment to promote bone resorption and the formation of osteoclasts." (PMID 38352248, 2023). "In light of previous reports and analysis of CRC single-cell sequencing data (GSE144735), we learned that IL11 is predominantly expressed by stromal cells other than tumor cells." (PMID 37365574, 2023). "By activating these pathways, previous studies revealed tumor-cell intrinsic activities of IL11 in cell proliferation, survival, motility, invasion and metastasis." (PMID 37365574, 2023). "Herein, we found that GPR84 was a new target of IL-11 that stimulates osteoclast formation in the tumor microenvironment, providing a novel mechanism in IL-11-mediated osteoclastogenesis." (PMID 36593458, 2023). "Our data show that, in turn, increased IL11 and POSTNi4 respectively contribute to enhanced tumor initiation and resistance to therapy, thus providing original insights on the mechanism behind relapses in CRC patients that fail to respond to platinum-based CT." (PMID 36765091, 2023). "Herein we aimed to reveal a novel function of IL-11 through STAT3 signaling in regulating tumor immune evasion." (PMID 37365574, 2023). "It is likely due to the differential effects of cross- and same-species recombinant IL11 that a later study utilizing same-species rhIL11 concluded IL11 to be tumor promoting, while an earlier study that used cross-species rhIL11 concluded otherwise." (PMID 35883698, 2022). "In sporadic gastrointestinal cancers, the IL-11/STAT3 signalling axis is a powerful tumour progressor." (PMID 36615513, 2022). "Some studies have found that the immune score of tumor tissue and serum IL-6, IL-11, or CD4 + /CD8 + T cells can also reflect the immune-inflammatory state, but the method is costly, inconvenient, and difficult to apply in clinical practice." (PMID 35866083, 2022). "Further in-depth studies into the pathophysiological effects of IL11 on stromal-tumor interaction in NSCLC are warranted and current available literature highlights the potential value of IL11 detection as a diagnostic and prognostic biomarker in NSCLC." (PMID 35883698, 2022). "Our data suggested that the knockdown of GPR81 impaired osteolysis and tumor growth partly because of a decrease in the expression of osteolytic cytokines, including IL-6 and IL-11." (PMID 35428832, 2022). "The pro-inflammatory cytokines IL-6 and IL-11 are produced by multiple cell types within the tumor microenvironment, such as tumor-infiltrating immune cells, stromal cells and tumor epithelial cells." (PMID 35053592, 2022). "In this process, CAFs can recruit immunosuppressive cells, including myeloid-derived suppressor cells (MDSCs) and, through the induction of cytokines such as IL-6 and IL-11, and participate in tumor immune evasion mechanisms." (PMID 36212154, 2022). "Interleukin 11 (IL-11) is involved in various stages of tumor development, including proliferation, angiogenesis, resistance to radio and chemotherapy, and inhibition of apoptosis." (PMID 35884907, 2022).
tumor (continued). "Similar results of elevated IL11 mRNA expression by RT-qPCR in tumor tissues have also been noted in several small studies." (PMID 35883698, 2022). "In human lung tumor tissue samples, IL11 is found to co-localize with ACTA2-positive cells (a marker of myofibroblasts), and single-cell RNAseq analyses showed that IL11 gene was expressed in both tumor cells and fibroblasts." (PMID 35883698, 2022). "Interleukin-11 (IL11) is a pleiotropic cytokine that has recently emerged as a tumor-promoting biomarker for cancer." (PMID 35883698, 2022). "Studies in animal models of spontaneous gastrointestinal cancer with hyperactive gp130 signaling, mediated via IL-11, show that Bazedoxifene treatment suppressed tumor growth via STAT3 mechanisms." (PMID 35053592, 2022). "The sources of IL11 in lung tumors comprise tumor cells, as well as stromal cell types such as fibroblasts, airway smooth muscle and epithelial cells." (PMID 35883698, 2022). "Besides, the blockade of IL-11 signaling with IL-11Rα antibody caused the reduction of EC cell viability and proliferation and impairment to cell metastasis in vitro, together with the inhibition of tumor growth and induction of cell apoptosis in EC xenograft models." (PMID 36531027, 2022). "Multiple in vitro studies confirm that IL11 activates known tumor-promoting signaling pathways and clinical studies link increased IL11 expression to poorer prognosis." (PMID 35883698, 2022). "IL11 secretion by fibroblasts is an important medium for NSCLC tumor growth and mediates fibroblast-tumor cell crosstalk." (PMID 35883698, 2022). "Although, we have evaluated the role of IL-11 signaling on immune cell activity in primary tumors using CRC models to demonstrate a prominent role of IL-11 in mediating CD4+ T cell-dependent immune-evasion in the tumor microenvironment." (PMID 35053592, 2022). "Briefly, tumor cell-derived factors (e.g., parathyroid hormone-related protein (PTHrP) and interleukin 11 (IL-11)) alter the RANKL/OPG ratio in favor of osteoclast activity." (PMID 35158995, 2022). "In subsequent studies, the same group demonstrated that hypoxia downregulated miR-495 and miR-5688 to enhance IL11 expression and promote tumor progression, showing that IL11 is especially important for tumor growth during tumor hypoxic conditions." (PMID 35883698, 2022). "Co-cultures of tumor-associated neutrophils (TANs)/TAMs with iCCA cells promoted tumor progression through OSM and IL-11 production by TANs and TAMs, respectively." (PMID 36077744, 2022). "In the case of bone osteolytic metastasis, it has been proposed that TGFβ released from bone matrix resorption stimulates tumor cells to produce PTHrP and IL-11, both promoting tumor growth and exacerbating osteolysis." (PMID 36497429, 2022). "One study found that IL11 was elevated in tumour samples compared to matched normal breast tissue, regardless of subtypes and grade." (PMID 34834425, 2021). "PI3K (PhosphatidylInositol 3-Kinase)-γ inhibition reduces IL-11 accumulation in the tumor ME, which mimics the TMZ response of the so-called “exceptional responders” whose tumors show a reduced trafficking and infiltration of GAMs." (PMID 34646780, 2021). "Immunohistochemistry (IHC) revealed that IL-11+ cells appeared in the stroma surrounding tumor cells." (PMID 33863879, 2021). "Interleukin (IL)-11 is a member of the IL-6 family of cytokines and is involved in multiple cellular responses, including tumor development." (PMID 33863879, 2021). "Although the IL(R)-based signature exhibited powerful predictive ability, these signature members themselves (IL-7R, IL-5RA, IL-20RB, IL-11, and IL-22RA1) were rarely reported to be used to predict tumor prognosis." (PMID 34497605, 2021). "Future scRNA-seq analysis will further characterize heterogeneous populations of IL-11+ cells in the tumor microenvironment." (PMID 33863879, 2021).
tumor (continued). "Tumor-derived TGFβ induces Il11 expression in stromal fibroblasts in a paracrine manner, whereas enforced expression of TGFβ in tumor cells promotes metastasis in tumor xenograft model." (PMID 33863879, 2021). "These cells are able to produce inflammatory and chemoattracting mediators such as CXCL12 and IL-11, both of which contribute to enhanced osteoclastogenesis and tumor cell homing to bone." (PMID 34064859, 2021). "Animal studies using triple-negative human BC xenografts including IL11-overexpressing subclones have supported the role of IL11 in tumour growth, metastasis and angiogenesis." (PMID 34834425, 2021). "Tumor cells produce many factors that stimulate osteolysis, such as PTHrP, IL-1, IL-6, IL-8, IL-11, and transforming growth factors, which directly inducing RANKL-mediated osteoclast differentiation and maturation." (PMID 34168981, 2021). "IL-11 is a multifunctional member of the IL-6 family, contributing to hematopoiesis, bone development, tissue repair, and tumor development." (PMID 33863879, 2021). "Taken together, these data demonstrate that MAFF is a positive regulator of tumor cell invasion and metastasis by activating IL11/STAT3 pathways when binding to BACH1, especially under hypoxic conditions." (PMID 34262028, 2021). "The RANKL/RANK system is also affected by tumor-secreted IL-11, which increases the RANKL level while decreasing the osteoprotegerin and PTHrP levels." (PMID 34212564, 2021). "The tumor cells secreted a few C/Cs on the panel, including exclusive secretion of IL-11, and shared secretion of CX3CL1, LIF and TIMP-1 with the fibroblasts." (PMID 34572807, 2021). "Interleukin-11 (IL-11), a tumor-motivator, augments the activities of the GP130-Janus kinase network to fuel the tumorigenesis of epithelial tumors, including BC." (PMID 33917233, 2021). "Simultaneously, YTHDF2 exerts an inhibitory effect on HCC, inhibiting growth of tumor cells and vessels by processing interleukin 11 (IL11) mRNA and serpin family E member 2 (SERPINE2) mRNA." (PMID 34105069, 2021). "Several authors have, indeed, proposed COX-2 inhibitors (NS398, indomethacin, and dexamethasone) as drugs useful for suppressing IL-11-mediated osteolytic bone metastases of tumour cells." (PMID 34201209, 2021). "The prominence of IL-6 signalling in the liver as well as TGFβ-driven IL-11 signalling in supporting primary tumour growth and metastasis in preclinical models suggest that these cytokines play important roles in the outgrowth of hepatic metastases." (PMID 33669775, 2021). "Here, we demonstrate that MAFF, which is induced by HIF-1 under hypoxia, binds with BACH1 and promotes tumor invasion and metastasis by transcriptionally activating IL11 and promoting STAT3 pathways." (PMID 34262028, 2021). "Results also showed that IL11 was higher in tumours with node-positive status and poorer prognosis and that a higher level of the cytokine was linked to poorer survival." (PMID 34834425, 2021). "Considering the bone metastases, interleukin (IL)-6, IL-8, IL-1β, and IL-11 mediate the crosstalk between bone cells and tumour cells acting on bone homeostasis: they show a bone trophic function and are regulators of bone remodelling." (PMID 34201209, 2021). "This pathway plays known anti-apoptotic and survival promoting roles in cancer, but it is also important as an inducer of invasion and proliferation of tumour cells acting downstream of IL-11." (PMID 34201209, 2021). "The presence of so many monocytes in the tumor is thought to be the result of macrophage chemotaxis caused by the expression of many cytokines, such as IL6, IL-11, IL-7, PTHrP, and TGFβ from neoplastic stromal cells." (PMID 34257573, 2021). "IL-11+ fibroblasts activate both tumor cells and fibroblasts via secretion of IL-11, thereby constituting a feed-forward loop between tumor cells and fibroblasts in the tumor microenvironment." (PMID 33863879, 2021).
tumor (continued). "In this context, the contribution of IL-11 appears peculiar, since it participates in the establishment of a vicious cycle of bone resorption and tumour growth, thus promoting bone colonization." (PMID 34201209, 2021). "Some studies identified the immunoscore of tumor tissue and serum interleukin-6 (IL-6), IL-11 or CD4+/CD8+ T cell also reflecting the immunoinflammatory status, but it is hard to be used in clinical practice due to the high cost and inconvenience." (PMID 34195071, 2021). "A deeper understanding of the role played by IL-11 in the various stages of tumour development and progression, in parallel with an improvement in the knowledge of the IL-11 signalling, will fully reveal its potential uses." (PMID 34201209, 2021). "Of note, alternatively activated macrophages and MDSCs are a major source of STAT3-activating cytokines such as IL6 and IL11, which form a paracrine loop to perpetuate a tumor-reactive microenvironment by acting on cancer cells." (PMID 34944848, 2021). "In particular, as IL-11 works on bone remodeling, it plays a relevant role in the osteolytic vicious cycle of bone resorption and tumour growth, which characterizes bone metastasis." (PMID 34201209, 2021). "Many tumor-promoting effects of IL-11, such as the promotion of cancer cell migration and invasion, have been linked to the STAT3 signaling cascade." (PMID 34917508, 2021). "IL11 enhances tumor cell proliferation, migration, EMT, and invasion of NSCLC cells via activation of STAT3, while depletion of IL11 significantly impairs the growth of NSCLC xenografts in mice and improves survival." (PMID 34944848, 2021). "Together, these results suggest there is intimate crosstalk between TGFβ and IL-11 and that TGFβ-induced tumor promotion is mediated, at least in part, by IL-11." (PMID 33863879, 2021). "During tumor metastasis, TGFβ1-stimulated CAFs secreted IL-11 to enhance the survival of CRC cells and increased the efficiency of organ colonization." (PMID 34735373, 2021). "Consistent with the IHC results, we found increased percentages of IL-11+ cells in the tumor tissues compared with non-tumor colon tissues from ApcMin/+;Il11-Egfp reporter mice by flow cytometry." (PMID 33863879, 2021). "We found that the IL-11+ cells in tumor tissues were mostly fibroblasts and a few epithelial cells and that deletion of Il11ra or Il11 attenuated CAC development in mice." (PMID 33863879, 2021). "New signaling pathways of interferon regulatory factors 1 (IRF-1) and 2 (IRF-2) and interleukin (IL)-1 family, IL-6, IL-11, IL-18, and interferons (IFNs) have been found within tumor microenvironments." (PMID 32887217, 2020). "Compared with GF mice, intestinal flora reconstruction or Bifidobacterium administration in GF mice significantly decreased the IL-11 expression in tumor." (PMID 32686598, 2020). "PTHrP can also directly induce OC differentiation and maturation by promoting secretion of IL-8, IL-6, IL-11, and other OC differentiation factors in tumor cells." (PMID 32269963, 2020). "RANKL and other osteoclast stimulating factors, including Interleukin-6 (IL-6) and Interleukin-11 (IL-11), are also secreted by tumour cells in bone metastases and OS, leading to an increase in bone resorption." (PMID 32752092, 2020). "Various cytokines (e.g., IL-6, IL-10, and IL-11) that are released into the microenvironment by tumor cells have also been shown to activate STAT3." (PMID 32188095, 2020). "The correct sentence should be: Tumor growth leads to the increased production of inflammatory cytokines and growth factors (mainly IL-1, IL-3, IL-6, IL-11, IL-23, and TNF-), and this perpetual process ensures immortality." (PMID 32293548, 2020). "The activation of NF‐κB leads to cytokine production, especially IL‐6, IL‐11 and IL‐22, providing an inflammatory environment for the growth of premalignant tumours." (PMID 32347623, 2020).
tumor (continued). "Within the tumour microenvironment (TME), cancer-associated fibroblasts (CAFs) secrete TGF-β and interleukin 11 (IL-11), an inducer of TGF-β that activates the oncogenic STAT3 pathway." (PMID 32585905, 2020). "PTHrP can also directly induce OC differentiation and maturation by promoting secretion of IL-8, IL-6, IL-11, and other OC differentiation factors by tumor cells." (PMID 32269963, 2020). "IL-6, IL-6sR, sTNFRI, and IL-11 are pro-inflammatory cytokines that contribute to angiogenesis, cell proliferation, tumor cell survival, exhaustion of effector T cells, and therapeutic resistance." (PMID 31510045, 2019). "When the expression levels of cytokines were examined in mice treated with AOM/DSS, we found increased mRNA expression levels of IL-6, IL-11, and TNFα in tumor tissues from Tg-tRXRα mice." (PMID 30931933, 2019). "Our findings provide compelling proof of concept to support the repurposing of bazedoxifene for the treatment of gastrointestinal cancers in which IL11 plays a tumor‐promoting role." (PMID 30885958, 2019). "These tumor epithelial cells showed higher expression of IL11 mRNA transcript when compared to that of IL6." (PMID 30885958, 2019). "The linear signaling cascade identified here comprising IL-11/IL-33/mast cells/macrophages/tumor cells should provide complementary molecular and cellular targets for the development of improved cancer therapies." (PMID 31227713, 2019). "Initial studies demonstrating that blocking IL-6 or IL-11 in HCC reduces tumor burden in mice have recently been published, and these encouraging first results now must be confirmed and translated into the clinic." (PMID 31683891, 2019). "Importantly, also Stat6-deficient tumor epithelia were characterized by increased Stat3 phosphorylation suggesting that enhanced gp130-dependent Stat3 activation triggered by IL-6 and IL-11 could account for the pro-proliferative, pro-tumorigenic phenotype of Stat6−/− mice (data not shown)." (PMID 30353167, 2019). "We have recently identified a hitherto unrecognized tumor‐promoting role for IL11 in mouse models of gastrointestinal cancers that arise in the mucosal epithelium of the stomach, small intestine, or colon." (PMID 30885958, 2019). "IL-11 expression has been demonstrated in the tumor tissue, and this expression pattern correlated with higher tumor node metastasis stage and was shown to be a prognostic factor for overall survival." (PMID 31683891, 2019). "The formation of osteolytic lesions is mediated by osteoclasts via the release of multiple osteoclastogenic factors from tumor cells (e.g., IL-1, IL-6, IL-11, PDGF, MIP1α, TNF, M-CFS, RANKL and PTHrP)." (PMID 30823602, 2019). "Once macrometastases are established, multiple factors such as M-CSF, TNF-α, IL-8 and IL-11 released from tumor cells drive osteoclasts to induce osteolytic lesions via the stimulation of RANKL." (PMID 30823602, 2019). "Malignant epithelial cells secrete cytokines, such as TNFα, IL-6, and IL-11, which inhibit the differentiation of the fibroblasts that surround tumor cells into adipocytes and increase their aromatase activity and expression." (PMID 31412584, 2019). "Our results indicate that YTHDF2 represses both tumor cells and tumor vasculature by processing IL11 and SERPINE2 mRNAs to decay." (PMID 31735169, 2019). "Various studies have shown that aberrant expression of the IL-6 family of cytokines, especially IL-6 and IL-11, is correlated with high tumour burden and is considered one of the most important cytokine families during tumourigenesis and metastasis." (PMID 31196220, 2019). "Meanwhile, others have proposed a role for IL11 signaling to enable metastatic spread and to retain tumor heterogeneity that underpins an aggressive phenotype." (PMID 30885958, 2019).